MMP1 (matrix metallopeptidase 1)
Diseases named in the same sentence as MMP1 in open-access papers (continued):
Sharing a sentence is not in itself a finding about the gene and the disease.
Arthritis (continued). "According to a study of adjuvant-induced arthritis in rats’ synovium, inhibition PPAR-γ expression by T0070907 or PPAR-γ siRNA could significantly promote the proliferation of fibroblast-like synoviocytes and expressions of c-Myc, Cyclin D1, MMP-1, and MMP-9, except for TIPM-1." (PMID 33397492, 2021).
pancreatic cancer (42 papers, 1999 to 2026). "MMP1 can also promote the development of pancreatic cancer 38, even become a potential diagnostic marker for pancreatic cancer." (PMID 35414794, 2022). "↑ uPA, ↑ MMP-1 and ↑ IL1-R1 in human pancreatic tumours. ↑ MMP-1 expression associated with ↑ PDAC tumour stage." (PMID 35204653, 2022). "CONCLUSION: MMP1 is an independent prognostic biomarker that drives pancreatic cancer progression through direct oncogenic effects and modulation of the tumor immune microenvironment." (PMID 41680671, 2026). "After further verification, it was determined that MMP1 was significantly upregulated in pancreatic cancer tissue and correlated with poor prognosis in patients." (PMID 41680671, 2026). "For example, pancreatic cancer cells secrete MMP1, which activates the protease‐activated receptor 1 (PAR1) in pancreatic neurons." (PMID 41556039, 2026). "In vitro functional assays confirmed that MMP1 knockdown in pancreatic cancer cells suppressed proliferation, migration, and invasion, while promoting apoptosis." (PMID 41680671, 2026). "The knockdown of MMP1 in pancreatic cancer cell lines decreased the expression of ductal markers such as SOX9 while the overexpression of MMP1 in hTERT-HPNE increased the expression of ductal markers, suggesting its function of maintaining ductal identity." (PMID 40092486, 2025). "In comparison to MMP1 activity, uPA activity increased steadily for pancreatitis, metastatic pancreatic cancer, and localized pancreatic cancer, respectively." (PMID 40292193, 2024). "MMP1 activity was significantly different for all 4 groups tested, which indicated MMP1 to be a promising candidate for both pancreatic cancer and pancreatitis detection as well as pancreatic cancer staging." (PMID 40292193, 2024). "Here, the purpose of this study was to investigate the prognostic and immunological roles of MMP1 in pan-cancer and confirm cancer-promoting effect in pancreatic cancer." (PMID 36727076, 2022). "Compared with HPDE, WB results suggested that MMP1 protein had a high expression in pancreatic cancer cells." (PMID 36727076, 2022). "In another study, MMP-1 induced perineural invasion in pancreatic cancer via MMP-1/protease-activated receptor-1/substance P/neurokinin 1 receptor (MMP1/PAR1/SP/NK1R) paracrine loop, which was activated by Akt." (PMID 35586209, 2022). "In summary, our single-cell RNA sequencing and bioinformatics analysis identified several highly variable genes including IFI27, KRT18, KRT19, MMP1, MMP3, and NEFL, whose expression is associated with a shorter overall survival of pancreatic cancer patients." (PMID 36010660, 2022). "We also utilized biological experiments to validate the cancer-promoting effect of MMP1 in pancreatic cancer." (PMID 36727076, 2022). "We also obtained the immunohistochemical pictures of MMP1 expression levels in pancreatic cancer from the HPA database." (PMID 36727076, 2022). "A recent study reported that MMP1 promotes the metastasis of PC and that the inhibitory regulation of MMP1 with endogenous microRNA can attenuate the metastatic ability of pancreatic cancer." (PMID 35892941, 2022). "At last, we proved the MMP1 expression and cancer-promoting function in pancreatic cancer using biological experiments." (PMID 36727076, 2022). "Periostat, a broad spectrum MMPI with higher specificity at MMP1, 2, 8 and 9, has entered phase II trials for resectable pancreatic cancer." (PMID 33809973, 2021). "manifested that miR-623 inhibited pancreatic cancer metastasis in vitro and in vivo through targeting matrix metalloproteinase-1 (MMP1)." (PMID 32766708, 2020). "Recent reports have emphasized the significance of MMP-1 expression in pancreatic cancer and its correlation with poor patient prognosis." (PMID 28881737, 2017). "In corresponding serum samples, we identified serum-derived MMP-7 and MMP-12 as strong classifiers to diagnose patients and tumor-derived PDGF-BB and MMP-1 as potential prognostic biomarkers in pancreatic cancer." (PMID 25483099, 2014).
pancreatic cancer (continued). "Consistent with their presumptive role as biomarkers, we have identifed MMP-1,-3,-7,-9,-10 and 12 as being upregulated in the serum of patients with pancreatic cancer, as compared to a cohort of healthy donors." (PMID 25483099, 2014). "MMP-1,-3,-7,-9,-10 and -12 were significantly upregulated in patients with pancreatic cancer (p < 0.0001, respectively), whereas MMP-2 was significantly decreased in the cancer patient group (p < 0.0001)." (PMID 25483099, 2014). "Despite the relatively low efficiency of Runx2 silencing in the tested cell lines, there was a significant change in the expression of several target genes such as SPARC and MMP1 in IPSCs and Panc-1 pancreatic cancer cells." (PMID 17876328, 2007). "Runx2 – in turn – suppresses the transcription of extracellular matrix modulators such as SPARC and MMP1, and thereby influences the pancreatic cancer microenvironment." (PMID 17876328, 2007). "Therefore, this study reveals the MMP1 expression and prognosis in human cancer, the relationship between MMP1 expression and tumor immunity, and the cancer-promoting effect of MMP1 in pancreatic cancer." (PMID 36727076, 2022). "However, the relationship between MMP1 and pancreatic cancer is rarely studied, especially in the acidic microenvironment of pancreatic cancer." (PMID 35414794, 2022). "Finally, molecular biology experiments were carried out to prove the cancer-promoting effect of MMP1 in pancreatic cancer." (PMID 36727076, 2022). "To validate the function of MMP1, we chose human pancreatic cancer for further investigation." (PMID 36727076, 2022). "Finally, molecular biology experiments confirmed the cancer-promoting effect of MMP1 in pancreatic cancer." (PMID 36727076, 2022). "Immunohistochemical results showed that MMP1 was overexpressed in pancreatic cancer." (PMID 36727076, 2022). "In pancreatic cancer cells, arginine starvation decreased metastasis by inhibition of MMP-1/9." (PMID 35321317, 2022). "Finally, to shed light on the mechanistic background, we performed qRT-PCR for established JNK target genes, including c-Jun, Survivin, CKD1, MMP1, and c-Myc, in untreated and low-dose (0.5 μM) JNKi-treated pancreatic cancer cells." (PMID 26840266, 2016). "Moreover, MMP1/PAR1 axis contributed to the perineural invasion (PNI) of pancreatic cancer cells." (PMID 34753916, 2021). "However, MMP1/PAR1 axis was reported to activate PI3K/AKT pathway in pancreatic cancer." (PMID 34753916, 2021). "In another study, the presence of stromal fibroblasts increased pancreatic cancer cell expression of a set of genes linked to tumor cell invasion, including cyclooxygenase 2 (COX-2)/prostaglandin-endoperoxide synthase 2 (PTGS2), hyaluronan synthase 2 (HAS2), and matrix metalloproteinase-1 (MMP-1)." (PMID 29903049, 2018). "In pancreatic cancer, RUNX2 has been shown to regulate the transcriptional activity of the extracellular matrix proteins SPARC and MMP1, thereby influencing the tumor microenvironment." (PMID 40386045, 2025). "In pancreatic stellate cells, the major sources of CAFs in pancreatic cancer, RLN2 induced MMP-1 and MMP-7 expression." (PMID 40666525, 2025). "It has also been demonstrated that PKD2 mediates cell invasion through the expression and secretion of MMP-1 in glioblastoma and MMP-7 and MMP-9 in pancreatic cancer." (PMID 39408603, 2024). "MMP1, MMP2 and MMP9, as well as their inhibitors, TIMP1 and TIMP2, were detected in pancreatic cancers, and their concentrations correlated with tumor grade, tumor size, invasive characteristics, and metastasis." (PMID 23744510, 2013). "MMP1, MMP2, MMP7, and MMP9 have also been shown to be expressed in pancreatic tumor, but the effect of cysteamine on protein and mRNA levels for all these MMPs was not examined except for MMP9." (PMID 22532830, 2012).
pancreatic cancer (continued). "Studies have shown that MMP-1, MMP-2, MMP-7, MMP-9, membrane type 1-MMP (MT1-MMP), MT2-MMP, and MT3-MMP are overexpressed in pancreatic cancer tumors, while MMP-2, MMP-7, and MMP-9 have been identified as potential biomarkers of pancreatic cancer." (PMID 34809634, 2021).
atherosclerosis (38 papers, 2007 to 2025). A disease characterized by the build-up of fatty material and calcium deposition in the arterial wall resulting in partial or complete occlusion of the arterial lumen. "Although implicated in neuronal cell death, MMP-1 has also been closely linked to advanced atherosclerotic plaques and has been postulated to exacerbate atherosclerosis by degrading plaques, which leads to a cycle of plaque expansion and rupture." (PMID 27529234, 2016). "Several genetic association studies on the role of specific MMP variants in atherosclerosis have been performed, especially with MMP1, MMP-3, and MMP-9." (PMID 23365489, 2013). "Findings from mouse studies indicate that MMP1 can inhibit atherosclerosis, and recent human studies show that persons homozygous for a transcriptionally overactive allele of the MMP1 gene have a reduced risk of coronary heart disease." (PMID 21554699, 2011). "As previously reported, elevated MMP-1 is associated with AIS, while IP-10 and IL-23 are associated with atherosclerosis." (PMID 36698075, 2023). "It has been found that shear stress can induce the up-regulation of MMP1, thus promoting the occurrence and progression of atherosclerosis." (PMID 37491214, 2023). "This lncRNA inhibits VSMC and EC migration by downregulating the expression of MMP1, inhibiting atherosclerosis progression." (PMID 35328769, 2022). "Our IPA results showed that MMP-1 was increased in the AAA-high mCRP group during the activation of the atherosclerosis pathway." (PMID 34428207, 2021). "Consistently, MMP1-Abs levels were associated with aCI, TIA, AMI, and DM, all of which are related to atherosclerosis." (PMID 29464021, 2018). "While MMP-8 and MMP-10 have been related to atherosclerosis and brain ischemic, respectively, MMP-1, 2, 3, 9, and 12 have been most identified in the pathophysiology of IS." (PMID 27529234, 2016). "In this study we tried to find correlations of three MMP polymorphisms (–1607 1G/2G MMP1; –1612 5A/6A MMP3; –1562 C/T MMP9) with a higher risk of myocardial infarction and formation of atherosclerosis plaque." (PMID 23274712, 2013). "A beneficial role for MMP-1 has also been observed in atherosclerosis, whereby the active digestion of interstitial fibrillar collagen (types I, II, and III) by this enzyme affected cell differentiation and impaired cell migration." (PMID 17311017, 2007). "Here we found an increased expression of MMP-1 and MMP-12 associated with stimulated cell migration of macrophages induced by PFOS and PFOA, which supports the role of macrophages in PFAS-mediated development of foam cells and atherosclerosis." (PMID 40728694, 2025). "Studies also found the levels of MMP1, MMP3, and MMP12 were positive associated with the degree of atherosclerosis and plaque stability, acting as valuable biomarkers for clinical diagnosis and prognosis of atherosclerosis." (PMID 37006258, 2023). "Furthermore, lncRNA RP11-714G18.1 impairs VSMC migration in atherosclerosis through the LRP2BP-mediated downregulation of MMP1." (PMID 35328769, 2022). "MMP1 is believed to play an important role in the pathogenesis of atherosclerosis." (PMID 21554699, 2011). "Thus, we suggest that the deposition of mCRP on the aortic wall of the aneurysms may damage the aortic wall by inducing atherosclerosis through MMP-1." (PMID 34428207, 2021). "Interestingly, Atherosclerosis Signaling was the second highest IPA pathway, and includes genes previously associated with vascular inflammation, such as IL-37, SERPINA1, S100A8, selectin E/SELE, lipoprotein lipase/LPL, and MMP1/3/9." (PMID 26459294, 2015). "Therefore upregulation of MMP-1, -2, -3, and -9 may enhance intraplaque angiogenesis at the advanced stage of atherosclerosis in rabbits." (PMID 25233229, 2014). "The analysis also identified inflammation-related targets within lipid and atherosclerosis pathways, such as STAT3, MMP9, MMP1, and AKT1, emphasizing the role of chronic inflammation in atherosclerosis development." (PMID 39808649, 2025).
atherosclerosis (continued). "MMP-1 has been found to cleave PAR1 on the surface of platelets, affecting thrombogenesis and atherosclerosis." (PMID 41091221, 2025). "Later, emerging evidence indicated that MMP1/PAR1 axis participated in the pathogenesis of thrombosis, atherosclerosis, and serious cardiac events." (PMID 34753916, 2021). "Therefore, MMP1 may have a subtle regulatory effect on the pathogenesis of atherosclerosis." (PMID 29464021, 2018). "Mediators involved in atherosclerosis (CX3CL1/fractalkine, CCL8, M-CSF, CXCL5, CCL4, HGF), tissue remodeling (MMP-12, MMP-1, MMP-10) and angiogenesis (VEGF-A) were also increased in AD." (PMID 28821884, 2017). "The most important finding in this study is that in this rabbit model of atherosclerosis, MMP-1, -2, -3, and -9 were positively correlated and MMP-14 was negatively correlated with intraplaque angiogenesis at the advanced stages of atherosclerosis." (PMID 25233229, 2014). "By our transcriptomic data (MMP-1), a significant reduction in MMP-8 levels following BP consumption suggests a stabilizing effect on vascular integrity, potentially mitigating the progression of atherosclerosis." (PMID 40722877, 2025). "APOB and MMP1 were also added as core targets since they are both targets with large differential expression in GSE100901 and share the same metabolic pathway of lipids and atherosclerosis." (PMID 38905402, 2024). "The presence of higher circulating levels of MMP-1 and MMP-10 in patients with carotid stenosis compared to healthy controls is in line with previous studies, highlighting the relationship between atherosclerosis and MMPs." (PMID 32101136, 2020). "Upregulation of MMP-1, -2, -3, and -9 and downregulation of MMP-14 may contribute to intraplaque angiogenesis and plaque instability at the advanced stage of atherosclerosis in rabbits." (PMID 25233229, 2014). "In conclusion, as shown in this rabbit model of atherosclerosis, upregulation of MMP-1, -2, -3, and -9 and downregulation of MMP-14 may participate in intraplaque angiogenesis at the advanced stages of atherosclerosis." (PMID 25233229, 2014). "Previous reports demonstrated that MMP-1 and MMP-13 might be overexpressed in both human and experimental atherosclerosis." (PMID 23365489, 2013). "FLI1 regulates the expression of metalloproteases (MMP-1, MMP-3, and MMP-10) and the pro-inflammatory cytokine IL-10; therefore, during chronic inflammatory conditions, such as AR and atherosclerosis, FLI1 down-regulation could attenuate tissue damage associated with inflammatory responses." (PMID 39767648, 2024). "In addition, they demonstrated that CB-ECFCs were able to decrease the expression of mediators of inflammation and atherosclerosis produced by allogeneic lymphocytes and monocytes (IL-1β, IL-8, PGF, ALOX-5, TNFα, CSF-2, MMP-1, MMP-9) more significantly than adult ECFCs." (PMID 32381102, 2020). "Among this family of related proteases, MMP-1 (also called interstitial collagenase), MMP-2 (gelatinase-A), and MMP-9 (gelatinase-B) have been consistently described as significant contributors in several cardiovascular diseases including atherosclerosis, hypertension, CAD, and ACS." (PMID 23951304, 2013). "Of note, mice do not possess a homologue for MMP-1; therefore, MMP-1 does not affect mouse atherosclerosis." (PMID 30413026, 2018).
hepatocellular carcinoma (33 papers, 2008 to 2025). A malignant tumor that arises from hepatocytes. "MMP1 associated mechanisms, pathways, mutations and prognosis in hepatocellular carcinoma were evaluated." (PMID 35948625, 2022). "In vitro and in vivo assays demonstrated that circDLC1 inhibits metastasis in hepatoma cells by interacting with the RNA-binding protein HuR and reducing the stability of matrix metalloproteinases 1 (MMP1) mRNAs." (PMID 39596302, 2024). "This is further supported by studies demonstrating a lack of association between sex and the expression of CAV-1 and MMP-1 in patients with CHC or CHC-related complications, such as hepatocellular carcinoma." (PMID 36556936, 2022). "Our research demonstrated that MMP1 expression was upregulated in patients with hepatocellular carcinoma and correlated with poor survival." (PMID 35948625, 2022). "This study focused on a comprehensive analysis of MMP1 in hepatocellular carcinoma, specifically the prognosis and tumor-immune microenvironment." (PMID 35948625, 2022). "In this study, we confirmed that MMP1 is able to promote both the proliferation and metastasis of hepatoma cells." (PMID 33391541, 2021). "Our data proved that MMP1 possessed the inhibition capacity of invasion and migration in hepatoma cells." (PMID 33391541, 2021). "Snail1 is known to amplify MMP gene expression of MMP1, -2, -7 and -14 in hepatocellular carcinoma cells." (PMID 27588391, 2016). "HBx can increase the migratory phenotype of hepatoma cells through the up-regulation of matrix metalloproteinases-1 (MMP1) and MMP9." (PMID 21078198, 2010). "Furthermore, cirDLC1 is considered a good prognosis marker since its upregulation not only decreases MMP-1 expression but also reduces hepatoma cells’ proliferation, invasion, and migration abilities." (PMID 38069210, 2023). "Likewise, the interaction of HuR with MMP-1 can be disturbed by the circular RNA cirDLC1 in hepatocellular carcinoma cells (HCC), causing an increase in MMP-1 transcript degradation." (PMID 38069210, 2023). "However, the relationship between MMP1 gene expression, tumor-immune microenvironment and prognosis in hepatocellular carcinoma patients remains mostly unclear." (PMID 35948625, 2022). "In addition, several studies reported the prognostic value of MMPs in cancer, such as MMP11 in PC, MMP2 in hepatocellular carcinoma, MMP1 in cervical squamous cell carcinoma, and so on." (PMID 33761734, 2021). "Functionally, as revealed by scratch wound healing and transwell assays, knockdown of circDLC1 could promote the motility of hepatoma cells, while the promotion could be blocked by deletion of MMP1." (PMID 33391541, 2021). "OPN and BSP are particularly helpful for assessing bone metastases in lung and prostate cancers, whereas other markers such as CTGF, IL-11, and MMP-1 have demonstrated greater prognostic significance in hepatocellular carcinoma (HCC)." (PMID 40426987, 2025). "The reduction in PKC alpha expression inhibits cell proliferation, migration and invasion in human malignant hepatocellular carcinoma (HCC) through downregulating MMP1 expression." (PMID 34445346, 2021). "Compared to NTA-MSCs, TA-MSCs from gastric cancer, lung cancer, pancreatic cancer and hepatocellular carcinoma (HCC) exhibit a notable elevation in cytokines like IL-6, IL-8 and TGF-β, along with genes including MMP1, S100A4, GREM1, and LOXL2, all of which are associated with tumorigenesis." (PMID 40676710, 2025). "In terms of immune cell regulation, studies have found significant differences in MMP1 expression and immune cell infiltration levels in hepatocellular carcinoma (HCC), where high MMP1 expression positively correlates with DC, Th1/2 cells, endothelial cells, and monocytes." (PMID 39744064, 2024). "Snail, a zinc finger transcription factor, increases cancer invasion by upregulating members of the MMP family, such as MMP-1, MMP-2, and MMP-7, in hepatocellular carcinoma." (PMID 36522523, 2023).